POU5F1 (POU class 5 homeobox 1)
Diseases named in the same sentence as POU5F1 in open-access papers (continued):
Sharing a sentence is not in itself a finding about the gene and the disease.
psoriasis (8 papers, 2011 to 2025). An autoimmune condition characterized by red, well-delineated plaques with silvery scales that are usually on the extensor surfaces and scalp. "SNP rs3130457 in POU5F1 tags the classical HLA-C*0602 allele, while rs10484554 in HLA-C is the most significant SNP associated with psoriasis and psoriatic arthritis in European ancestry population." (PMID 22125590, 2011). "Previous studies have shown that a genetic polymorphism of POU5F1 is associated with psoriasis in Chinese population." (PMID 22125590, 2011). "Interestingly, POU5F1 polymorphisms have been associated with psoriasis in Polish and Chinese populations suggesting a link between this disease and OLFM4–POU5F1 interplay." (PMID 35218417, 2022). "In addition to classical HLA genes such as HLA-C, HLA-B and HLA-DQA2, we also find association of non-HLA genes in the MHC region such as POU5F1, NFKBIL1, NOTCH4, MICA, IER3 and OR12D2 with psoriasis." (PMID 22125590, 2011).
diabetes (7 papers, 2012 to 2025). "Importantly, no upregulation of progenitor markers, such as neurogenin 3 (NEUROG3), POU class 5 homeobox 1 (POU5F1), and nanog homeobox (NANOG) was found in T2D β-cells, in contrast to what was previously reported in diabetes mouse models." (PMID 38731945, 2024).
lymphoma (7 papers, 2014 to 2023). A malignant (clonal) proliferation of B- lymphocytes or T- lymphocytes which involves the lymph nodes, bone marrow and/or extranodal sites. "Second, we analyzed perturbation signatures of artificially induced overexpression of MYC in lymphomas of Eμ-Myc-transgenic mice as well as knock-out experiments of NANOG, POU5F1 and SOX2 in human embryonic stem cells." (PMID 29741575, 2018). "Second, we analyzed perturbation signatures of (i) mouse lymphomas with artificially induced MYC overexpression and (ii) knock-out experiments of NANOG, POU5F1 and SOX2 in human embryonic stem cells." (PMID 29741575, 2018). "Second, we analyzed perturbation signatures of (i) mouse lymphomas with artificially induced overexpression of MYC and (ii) knock-out experiments of NANOG, POU5F1 and SOX2 in human embryonic stem cells to examine if the different methods are able to identify the perturbed regulators." (PMID 29741575, 2018).
testicular cancer (7 papers, 2015 to 2022). A primary or metastatic malignant neoplasm that affects the testis. "Expression of POU5F1 (OCT4) and NANOG, which are known for their association with pluripotency in embryonic stem cells are also characteristic of GCNIS and derived invasive testicular cancers." (PMID 33805941, 2021).
type 2 diabetes (7 papers, 2015 to 2025). "We confirmed associations with type 2 diabetes for five of the seven SNPs (TMEM154-rs6813195, FAF1-rs17106184, POU5F1/TCF19-rs3130501, ARL15-rs702634 and ABCB9/MPHOSPH9-rs4275659)." (PMID 25799151, 2015). "A trans-ethnic meta-analysis of type 2 diabetes genome-wide association studies has identified seven novel susceptibility variants in or near TMEM154, SSR1/RREB1, FAF1, POU5F1/TCF19, LPP, ARL15 and ABCB9/MPHOSPH9." (PMID 25799151, 2015). "We examined the association of six SNP loci, rs6813195 near TMEM154, rs9505118 in SSR1, rs17106184 in FAF1, rs3130501 in POU5F1, rs702634 in ARL15, and rs4275659 near MPHOSPH9, identified by transethnic GWAS meta-analysis with susceptibility to type 2 diabetes in a Japanese population." (PMID 27115357, 2016). "We performed a replication study in a Japanese population to evaluate the association between type 2 diabetes and six susceptibility loci (TMEM154, SSR1, FAF1, POU5F1, ARL15, and MPHOSPH9) originally identified by a transethnic meta-analysis of genome-wide association studies (GWAS) in 2014." (PMID 27115357, 2016). "Similarly, transcripts of candidate genes for type 2 diabetes (Blk, C2cd4a, C2cd4b, Cdkn2a, Hnf1a, Mtnr1b, Pou5f1, Slc30a8) and type 1 diabetes (Cd69, Il2, IL27) were not expressed in the brain." (PMID 39920851, 2025). "Our results indicate that effects of the six SNP loci identified in the transethnic GWAS meta-analysis are not major among the Japanese, although SNPs in POU5F1 and MPHOSPH9 loci may have some effect on susceptibility to type 2 diabetes in this population." (PMID 27115357, 2016).
cervical squamous cell carcinoma (6 papers, 2019 to 2024). A squamous cell carcinoma arising from the cervical epithelium. "However, there are challenges in identifying specific markers for cervical squamous cell carcinoma (CCSC), including ABCG2, MSI1, PROM1 (CD133), ITGA6 (CD49f), KRT17 (CK17), SOX2, and Pou5f1 (OCT4)." (PMID 38651153, 2024).
gastric tumors (6 papers, 2012 to 2023). "Consistent with this, we found that SOX2, POU5F1 (a gene encoding OCT4) and ITGA6 were all strongly expressed in human gastric tumors examined, except that SOX2 was not expressed by MKN74 cell line." (PMID 24015244, 2013).
serous ovarian cancer (6 papers, 2012 to 2024). "ELF3 knockdown reduced SOX2 and POU5F1/OCT4 expression, whereas overexpression of ELF3 increased SOX2 and POU5F1 expression in high-grade serous ovarian cancer cells." (PMID 36289818, 2022).
gonadoblastoma (5 papers, 2013 to 2025). A mixed germ cell/sex cord-stromal tumor characterized by the presence of large germ cells which resemble seminoma cells and small cells which resemble Sertoli or granulosa cells. "One specific marker for gonadoblastoma and germ cell neoplasia in situ (GCNIS) is POU5F1, and prolonged expression of this marker is crucial to GCC development." (PMID 31721911, 2019).
acute myeloid leukemia (4 papers, 2020 to 2026). Acute myeloid leukemia (AML) is a group of neoplasms arising from precursor cells committed to the myeloid cell-line differentiation. "However, the prognostic value of POU5F1 was not obvious in the overall survival of acute myeloid leukemia patients." (PMID 32978904, 2020).
adenoma (4 papers, 2013 to 2023). A neoplasm arising from the epithelium. "Although SOX2 and POU5F1 expression in adenoma tissue and cell cultures was very low, it was detectable in all samples." (PMID 27340409, 2016).
cyst (4 papers, 2015 to 2025). A sac-like closed membranous structure that may be empty or contain fluid or amorphous material. "The results reveal that the columnar side of the asymmetric cyst is composed of cells that prominently retain the pluripotency marker OCT4 (also known as POU5F1), which is lost in the squamous cells." (PMID 28785084, 2017).
dysplasia (4 papers, 2011 to 2021). A usually neoplastic transformation of the cell, associated with altered architectural tissue patterns. "We saw an increase in POU5F1 expression in tissue with villous and high-grade dysplasia compared to other polyp tissue, but this increase was not statistically significant compared to normal tissue." (PMID 34452555, 2021).
mesothelioma (4 papers, 2020 to 2024). A usually malignant and aggressive neoplasm of the mesothelium which is often associated with exposure to asbestos. "This is the first study that extensively tested the expression of OCT4/POU5F1, NANOG and SOX2 genes and proteins in human mesothelium and mesothelioma." (PMID 32664372, 2020). "Unlike protein expression, the genes of pluripotency factors, POU5F1, NANOG and SOX2, were less expressed in mesothelioma than in mesothelium." (PMID 32664372, 2020). "Compared to normal mesothelium, mesothelioma exhibited higher expression of NANOG and SOX2 proteins and lower expression of POU5F1, NANOG and SOX2 genes." (PMID 32664372, 2020). "We showed for the first time in human mesothelioma that PI3K and AKT genes were in positive correlation with the expression of POU5F1, NANOG and SOX2, suggesting positive regulation at the level of gene expression." (PMID 32664372, 2020). "We tested the expression of OCT4/POU5F1, NANOG, SOX2, PI3K-AKT pathway and BCL2 genes and proteins in 65 samples of human mesothelioma and 19 samples of normal mesothelium." (PMID 32664372, 2020). "We demonstrated that human mesothelium and mesothelioma express NANOG and SOX2 proteins and POU5F1, NANOG and SOX2 genes." (PMID 32664372, 2020). "Human mesothelium and mesothelioma expressed SOX2, NANOG, PI3K and AKT genes and proteins and POU5F1 gene, whereby NANOG, SOX2 and phosphorylated (activated) AKT were upregulated in mesothelioma." (PMID 32664372, 2020). "Others have shown that H2O2 can upregulate POU5F1, NANOG and SOX2 in mesothelioma line." (PMID 32664372, 2020). "Unlike OCT4 protein, POU5F1 gene was expressed in both human mesothelium and mesothelioma, suggesting a posttranscriptional block in its expression in both tissues." (PMID 32664372, 2020). "Conversely, it has been also shown that POU5F1, NANOG and SOX2 are not expressed in mesothelioma cell lines." (PMID 32664372, 2020).
bone tumors (3 papers, 2011 to 2025). "An EWSR1/POU5F1, EWSR1/PBX1 or EWSR1/ZNF444 fusion gene, or a rearrangement of the EWSR1 gene with unknown fusion partner, was detected in close to half of the soft tissue lesions, and in four out of five bone tumors." (PMID 22588017, 2011).
glaucoma (3 papers, 2021 to 2024). Increased pressure in the eyeball due to obstruction of the outflow of aqueous humor. "The use of the Oct4 (also known as Pou5f1), Sox2 and Klf4 genes (OSK) to reverse DNA methylation during glaucoma and restore vision strongly suggest that PRC2 may be involved in glaucoma as well." (PMID 34502238, 2021).
lipoma (3 papers, 2018 to 2025). A benign, usually painless, well-circumscribed lipomatous tumor composed of adipose tissue. "There is a lack of data in the literature on Oct4 expression in LDSCs, however, there are some reports on expression of POU5F1 in lipoma tissue, and it has been shown that this gene is up-regulated in lipoma compared to the normal adipose tissue." (PMID 30544806, 2018). "Although there is lack of data in the literature on Oct4 expression in LDSCs, there are some reports on POU5F1 expression in lipoma tissue, and it was shown that this gene is up-regulated in lipoma compared to the normal adipose tissue." (PMID 30987193, 2019).
myocardial infarction (3 papers, 2020 to 2022). Gross necrosis of the myocardium, as a result of interruption of the blood supply to the area, as in coronary thrombosis. "On the other hand, HIF-2α and POU5F1 (OCT4) could collaboratively promote the survival and differentiation of embryonic-like mesenchymal stem cells in myocardial infarction to repair the damaged myocardia." (PMID 32565767, 2020).
papillary thyroid cancer (3 papers, 2013 to 2021). "In thyroid tumors, including papillary thyroid carcinoma, CD44 resulted the best marker for the identification of thyroid stem cells, that also expressed POU5F1." (PMID 34219203, 2021).
gestational trophoblastic disease (2 papers, 2015 to 2017). "For example, alterations in POU5F1 expression have been associated with gestational trophoblastic disease." (PMID 28615018, 2017). "Interestingly, residual expression of POU5F1 is detected throughout the first trimester and in term placenta tissues, and reduction in this residual expression is associated with gestational trophoblastic diseases." (PMID 26288817, 2015).
malignant rhabdoid tumor (2 papers, 2020 to 2022). "Accumulation of the chromatin remodeling protein SMARCA4 (BRG1) leads to the loss of PRCs at Pou5f1 in mouse cells and at INK4b-ARF-INK4a in human malignant rhabdoid tumor cells." (PMID 31947658, 2020).
small cell carcinoma (2 papers, 2019 to 2021). A neuroendocrine carcinoma composed of small malignant cells which are often said to resemble "oat cells" under the microscope. "Cancer de-differentiation transforms luminal-like (differentiated) adenocarcinoma into less luminal-like and more stem-like (undifferentiated) small cell carcinoma through a sequential activation of stem cell transcription factors (scTF) POU5F1, LIN28A, SOX2 and NANOG." (PMID 34911496, 2021). "Previously, we reported the presence of scTF LIN28A, NANOG, POU5F1 and SOX2 in a small cell carcinoma patient-derived xenograft (PDX) line LuCaP 145.1 but absent in adenocarcinoma PDX lines." (PMID 31146720, 2019). "Newly available non-adenocarcinoma/small cell carcinoma PDX LuCaP lines were analyzed for expression of stem cell transcription factors (scTF) LIN28A, NANOG, POU5F1, SOX2, which are responsible for reprogramming or de-differentiation." (PMID 31146720, 2019).
amenorrhea (1 paper, 2020). The absence of menses in a woman who has achieved reproductive age. "We also identified a second combination of POU5F1 (c.87G>T;p.Trp29Cys) and HK3 (c.2026C>T;p.Pro676Ser) in POI-15 presenting with secondary amenorrhea." (PMID 33095795, 2020).
biliary tract cancer (1 paper, 2023). "Vismodegib was shown to reduce OCT4 (POU5F1) expression in biliary tract cancer Mz-ChA-1 and Sk-ChA-1 cells." (PMID 37445628, 2023).
congenital heart disease (1 paper, 2015). A heart disease that is present at birth. "However, whether the genetic variations in OCT4 coding gene, POU5F1, confer the predisposition to congenital heart disease (CHD) is unclear." (PMID 26507003, 2015).
COVID-19 (1 paper, 2021). A disease caused by infection with severe acute respiratory syndrome coronavirus 2. "Both POU5F1 and AIRE genes have been mentioned in SARS133 literature-associated genes from Geneshot GeneRIF and also reported as up-regulated genes in COVID-19 infected bronchoalveolar lavage from patients and in COVID-19 patient’s whole blood (GSE166552)." (PMID 34407143, 2021).
Fanconi anemia (1 paper, 2020). Fanconi anemia (FA) is a hereditary DNA repair disorder characterized by progressive pancytopenia with bone marrow failure, variable congenital malformations and predisposition to develop hematological or solid tumors. "The comparative analysis revealed that loss of POU5F1 and some of the components of the Fanconi anemia core complex also resulted in reduced cell viability in hESCs." (PMID 33228647, 2020).
fibromyalgia (1 paper, 2014). A chronic disorder of unknown etiology characterized by pain, stiffness, and tenderness in the muscles of neck, shoulders, back, hips, arms, and legs. "Fibromyalgia has been genetically linked to the HLA region (6p21.3) 63, which includes several genes associated with Notch signalling (e.g. Notch4, FKBP5, TNXB, MTCH1 and TNF-a) or with stem cell maintenance and proliferation (e.g. POU5F1, Flot1, MAPK14, Rgl2 and Rab44)." (PMID 25164209, 2014).
hyperplastic polyp (1 paper, 2021). A polyp found mainly in the stomach and colon. "In hyperplastic polyps (group 1), there was a significant decrease in the expression of PROM1 (p: 0.01), POU5F1 (p: 0.02), LGR5 (p: 0.01) and REX1 (p: 0.01) genes compared to the control group." (PMID 34452555, 2021).
metabolic syndrome (1 paper, 2023). A cluster of metabolic risk factors for CARDIOVASCULAR DISEASES and TYPE 2 DIABETES MELLITUS. "PIK3R2, STRA8, FLT1, DMRT1, FGF22, NR5A2, and FLT were up-regulated and PRDM14, POU5F1, and KDR were down-regulated in metabolic syndrome after exercise." (PMID 37053002, 2023).
mucinous carcinoma (1 paper, 2016). "The expression rate of POU5F1/Oct-4 was lower in DCIS than in mucinous carcinoma, IDC and Paget’s disease; but the difference was not statistically significant (40.00 % vs. 44.44 % vs. 57.65 % vs. 100.00 %; P = 0.216)." (PMID 26931354, 2016).
pterygium (1 paper, 2021). A wedge-shaped fibrovascular lesion arising from the bulbar conjunctiva and extending to the cornea. "We found that genes encoding transcription factors MYC, KLF4, POU5F1 and PITX1 were upregulated in pterygium." (PMID 34769520, 2021). "POU5F1 is one of the top upregulated genes in pterygium as is a second transcription factor PITX1." (PMID 34769520, 2021). "This analysis suggests an expansion of cells from the corneal limbal epithelial compartment in pterygium, and identifies KLF4, MYC and POU5F1 and PITX1 as specifically involved." (PMID 34769520, 2021).
retinal dystrophies (1 paper, 2025). "Since Pou5f1 overexpression only weakly and transiently induces proliferation in adult Müller glia, this reduces the potential oncogenic risk, and may ultimately prove to be relevant for the design of cell-based regenerative therapies for treating retinal dystrophies." (PMID 40388211, 2025). "This study demonstrates that viral-mediated overexpression of Pou5f1 induces neurogenic competence in adult mouse Müller glia, identifying mechanisms that could be used in cell-based therapies for treating retinal dystrophies." (PMID 40388211, 2025).
Wilms tumor (1 paper, 2008). An embryonal neoplasm characterized by the presence of epithelial, mesenchymal, and blastema components. "Important for their relation to Wilm's Tumor, several of these TFs have previously been implicated in cancer (NANOG, GLI1, E2F1, POU5F1/OCT4, SPI-1, YY-1, GATA1, and C/EBP-β)." (PMID 18564415, 2008).